FASN (fatty acid synthase)
Diseases named in the same sentence as FASN in open-access papers (continued):
Sharing a sentence is not in itself a finding about the gene and the disease.
breast cancer (continued). "In addition to these two words, the other top 10 keywords were “expression” (151 times), “breast cancer” (136 times), “metabolism” (108 times), “lipid metabolism” (102 times), “fatty-acid synthase” (78 times), “growth” (73 times), “cancer” (67 times), and “cells” (66 times)." (PMID 37179822, 2023). "A recent study showed that FASN inhibition increases mitochondrial priming and enhances breast cancer cell sensitivity to BCL2-targeting BH3 mimetics which may directly activate the apoptotic machinery and generate more potent and longer-lasting antitumor responses in a clinical setting." (PMID 38049490, 2023). "Interestingly, previous work suggested that the accumulation of Mal-CoA, rather than the inhibition of FASN itself, is the underlying cause in FASN-inhibitor-induced toxicity in breast cancer cells." (PMID 37563253, 2023). "Whether FASN expression had impact on the prognosis in patients with breast cancer is elusive." (PMID 37124526, 2023). "In addition, FASN blockade may promote synergistic chemosensitization of breast cancer cells to other treatments, such as paclitaxel, adriamycin, 5-FU, and vinorelbine." (PMID 36059650, 2022). "Similarly, fatty acid synthase was identified as the tumor antigen OA-519 in aggressive breast cancer, and may play an importance role of fatty acid biosynthesis for cancer cell growth and survival." (PMID 34638954, 2021). "Furthermore, EGCG treatment reduces FASN expression levels in selected breast cancer cell lines." (PMID 33742137, 2021). "Thus, one might expect that inactivation of FASN signaling in endocrine-resistant breast cancer with high FASN expression leads to restoration of endocrine sensitivity." (PMID 33800852, 2021). "To characterize whether the ability of pharmacological FASN blockade to impede the tamoxifen-enhanced tumorigenicity of ER+/HER2+ breast cancer cells involved a differential regulation of ERα expression, we evaluated the effects of FASN inhibition on the status of ERα by immunoblotting." (PMID 33800852, 2021). "Nonetheless, because the PR isoform ratio is a proxy for the molecular signature and endocrine therapy responsiveness of PR+ breast cancer cells, our findings might illuminate new PR-B/FASN-centered predictive and therapeutic modalities in luminal breast cancer intrinsic subtypes." (PMID 33335078, 2020). "Our results lead us to propose that the PR isoform-specific regulation of distinct regulatory responses in the cross-talk between prolactin and FASN might be involved in the diverse phenotypic outcomes arising from the prolactin/PRLR signaling axis in luminal breast cancer." (PMID 33335078, 2020). "Moreover, FASN overexpression induces resistance to antitumoral drugs such as adriamycin and mitoxantrone in breast cancer cells, gemcitabine-resistant pancreatic cells, cisplatin-resistant ovarian cancer cells, and radiotherapy resistant head and neck squamous cell carcinomas." (PMID 32211323, 2020). "As a new generation of FASN inhibitors has recently entered the clinic, our study suggests that targeting FASN could be therapeutically exploited for the clinico-molecular management of the poor prognosis luminal-B subtype of ER+ breast cancer patients." (PMID 33081219, 2020). "In ER-positive/PR-negative luminal B-like breast cancer cells, however, FASN signaling might be co-opted as a negative regulator of the epithelial cell phenotype and, accordingly, its blockade might promote the restoration and activation of prolactin/PRLR-driven differentiation programs." (PMID 33335078, 2020). "Moreover, FAs’ synthesis could have an important role in the pathogenesis of breast cancer, because breast cancer cells present an increased expression of the multifunctional enzyme fatty-acid synthase (FASN)." (PMID 31052256, 2019).
breast cancer (continued). "FASN has long been recognised as an attractive target for cancer as its inhibition has antiproliferative effects in cancer cells and the antiestrogens fulvestrant and tamoxifen are the most common therapeutic approaches for inhibiting ERα signalling in ER-positive breast cancer patients." (PMID 29331414, 2018). "Interestingly, a recent study showed that FASN inhibition causes breast cancer cell death independent of its effects on inhibiting lipogenesis." (PMID 28290443, 2017). "In breast cancer, this phenomenon has been correlated with the presence of estrogen/progesterone receptors, which are well-known modulators of cell signaling pathways involved in cell cycle, angiogenesis, and metastasis but also known to trigger lipogenic pathways, including the FASN signaling." (PMID 28883835, 2017). "In addition, in breast cancer cells undergoing EMT an increased expression of FASN resulted in saturated FAs accumulation, which are then relocated to the cell membrane and regulate lipid rafts organization, resulting in the activation of the EMT-inducer VEGF/VEGFR2 signaling." (PMID 28352611, 2017). "Since it has been reported that estradiol increases FASN expression in breast cancer cells and that insulin increases FASN expression in liver, we examined whether fatty acids could also decrease the estradiol- or insulin-induced increase in FASN expression in MCF-7 breast cancer cells." (PMID 29282029, 2017). "However, natural product-derived FASN inhibitors, such as bakuchiol, may provide new therapeutic moieties for breast cancer patient care." (PMID 29093680, 2017). "However, all these studies were conducted in osteosarcoma cells and which of them plays the most important role in regulating FASN expression in breast cancer remains unclear." (PMID 27713175, 2016). "So we proposed that FASN might mediate the effect of leucine deprivation on breast cancer cells." (PMID 27579768, 2016). "Therefore, we analyzed whether clofibrate treatment stimulates/suppresses FASN in breast cancer cells." (PMID 26621841, 2016). "There is a very high probability that downregulation of FASN expression by OPG CRISPR/Cas9 knockdown might be due to an effect on these lipid metabolism genes which in turn would affect the lipid content in the breast cancer cells." (PMID 27270654, 2016). "Chemical inhibition of de novo fatty acid synthesis decreases the proliferation of cultured breast cancer cells, reduces activation of signaling pathways, and in some cases, slows the growth of xenograft tumors; and direct inhibition of FASN has been explored for cancer therapy." (PMID 25472762, 2014). "Therefore, inhibiting FASN represents a promising anticancer strategy in ER+/HER2+breast cancer." (PMID 24866893, 2014). "In addition, the regulation of protein stability and degradation by a signaling protein β-catenin in mantle cell lymphoma (MCL) as well as post-transcriptional regulation by ubiquitin-specific-protease 2a (USP2a) and isopeptidase proteins breast cancer cells also up-regulate the expression of FASN." (PMID 25255125, 2014). "In addition, we corroborate a FASN-ErbB loop, described in breast cancer." (PMID 22769244, 2012). "NF-YA and sterol regulatory element binding protein 1 (SREBP1) jointly regulate the expression of acetyl-CoA carboxylase (ACACA) and FASN, thereby promoting the adipogenesis of TNBC cells and the progression of breast cancer." (PMID 40256431, 2025). "We initially evaluated the FASN expression profiles in SK-BR-3, MCF-7, and MDA-MB-231 breast cancer cell lines." (PMID 40733158, 2025). "Trans-chalcone, a precursor of flavonoids, acts as a potent inhibitor of fatty acid synthase (FAS) and α-amylase, with notable antifungal and anticancer properties, including the ability to induce cell-cycle arrest and apoptosis in breast cancer cells." (PMID 40004065, 2025).
breast cancer (continued). "Analysis of the METABRIC database revealed that genes related to fatty acid metabolism, such as ACLY, CPT1A, FASN and SCD, are most highly expressed in HER2-positive breast cancer." (PMID 40303293, 2025). "Several studies have highlighted enzymes involved in de novo fatty acid biosynthesis, including ACLY, ACC, FASN, and SCD1, which are upregulated in breast cancer." (PMID 40002245, 2025). "Fatty acid synthase (FASN): FASN expression is upregulated in early-stage lung, prostate, and breast cancers, with further increases observed as cancer progresses." (PMID 41306968, 2025). "Besides, a decrease in the levels of main products of FASN, palmitic acid, stearic acid, and myristic acid, induced apoptosis in mouse embryonic fibroblasts by triggering p21 and Bax expressions, while treatments with the fatty acids reduced the apoptotic protein levels in breast cancer cells." (PMID 40133683, 2025). "Prior studies link FASN, GNAS, and IGHA1 to breast cancer progression and suggest prognostic potential." (PMID 41263940, 2025). "Other FASN inhibitors, including C75, EGFR, Fasnall, and TVB-3166, also demonstrate significant inhibitory effects on breast cancer, although they face limitations in clinical application." (PMID 40002245, 2025). "The interplay between ACSL4, FASN, and SCD underscores a coordinated lipid metabolism axis in BQ-driven breast cancer, with ACSL4 as the key effector of energy production, potentially supporting metastatic potential by providing energy for EMT and invasion." (PMID 40507798, 2025). "FASN was less expressed in JIMT1 and more expressed in BT474, SKBR3, and HCC1954 in four HER2-positive breast cancer cell lines." (PMID 40303293, 2025). "Although previous studies have reported that resveratrol downregulates FASN expression in HER-2-positive and FASN-overexpressing breast cancer SK-BR-3 cell line, the full scope of its anti-cancer potential remains to be clarified." (PMID 40733158, 2025). "Instances of overexpression have been noted for ACLY in breast carcinoma, ACC in hepatocellular carcinoma, FASN in pancreatic carcinoma, and SCD1 in ovarian cancer." (PMID 40956032, 2025). "The “HER2–FASN axis”, a two-way regulatory mechanism between HER2 and FASN, has been postulated to improve the metastasis, proliferation, and chemoresistance of breast cancer." (PMID 39791706, 2024). "In sum, these experiments demonstrate the necessary role of TAG stores in promoting metastatic breast cancer migration, and that the higher level of stored TAG requires upregulated FASN activity." (PMID 39678343, 2024). "Fatty acid synthase (FASN), a crucial enzyme required for FAS, is expressed at higher levels in breast cancer." (PMID 39791706, 2024). "Subsequently, we evaluated the metabolic and proliferative functions upon FASN and LDHA inhibition in breast cancer models." (PMID 39044184, 2024). "In breast cancer cells, it was found that circARL8B influenced the expression levels of ACC1, FASN, and FABP5." (PMID 38408962, 2024). "Key lipogenesis genes (SREBP1c, ACLY, ACC, FASN, and SCD1) are directly regulated by LXR, and their expression levels upon 1E5 treatment are shown to be downregulated in breast cancers." (PMID 38730603, 2024). "In contrast, the FASN inhibitor cerulenin reduced CPT1A expression only in NFYA wild-type cells, suggesting that NFYA regulates breast cancer malignant behavior by controlling de novo lipogenesis by regulating ACACA and FASN expression." (PMID 37268670, 2023). "It has been recently demonstrated that mTOR promotes FASN expression in HCC cells and in breast cancer cells." (PMID 36934087, 2023).
breast cancer (continued). "FASN and SCD1 are also considered therapeutic targets in many cancers, and SREBPs regulate breast cancer cell invasion and migration." (PMID 37885013, 2023). "It activates AMPK and down-regulates mTOR in breast cancer cells, subsequently inhibiting acetyl-CoA carboxylase α (ACACA) and fatty acid synthase (FASN)." (PMID 38001865, 2023). "Two metabolic enzymes, fatty acid synthase (FASN) and acetyl CoA carboxylase (ACC), which being involved in the de novo synthesis of fatty acid were found to be up-regulated in breast cancer." (PMID 37120513, 2023). "Targeting the up-regulation of FASN and ACC is an effective approach to limiting the growth, proliferation, and metastasis of breast cancer cells." (PMID 37120513, 2023). "TVB-2640 and PF-05175157 are inhibitors of FASN and ACC respectively, and have been used to treat breast cancer cells." (PMID 37120513, 2023). "Four studies reported a correlation between FASN expression and the DFS/RFS of breast cancer patients." (PMID 37124526, 2023). "Upon SRPK2 knockdown and inhibition, we observed a decrease in FASN protein and mRNA stability, respectively, in response to IGF-1 exposure that was specific to triple negative and HER2+ breast cancer cell lines." (PMID 36096767, 2022). "Natural FASN inhibitors are also available, the most studied of which is epigallocatechin gallate (EGCG), shown to inhibit the growth of breast cancer cells in vivo and in vitro." (PMID 35448537, 2022). "In a panel of samples with primary human breast cancer, SREBP-1c and FASN are increased and correlated with each other." (PMID 35912181, 2022). "IGF-1 exposure contributed to increases in FASN mRNA and protein expression in both MCF-7 and MDA-MB-231 breast cancer cells." (PMID 36096767, 2022). "The inhibition of FASN by the gallate derivatives of EGCG, which induced apoptosis in human breast cancer cells, has also been suggested to occur under the blocking of AKT and ERK1/2 phosphorylation." (PMID 35243817, 2022). "To investigate the role of IGF-1 induced SRSF-1 FASN regulation, we knocked down SRSF-1 by RNAi in breast cancer cells and performed RT-qPCR for FASN mRNA expression." (PMID 36096767, 2022). "FASN and ACCα expression are regulated at the translational level by PI3K-mTOR signaling pathway in HER2 overexpressing breast cancer cells (BT-474, SK-BR-3)." (PMID 36618350, 2022). "A FASN-targeted inhibitor, C75, boosted antitumor immune capacity and blockaded tumor proliferation under the setting with the PI3Kα inhibitor CYH33 in breast cancer." (PMID 36428733, 2022). "Simultaneous blocking FASN and HER2 pathways showed significantly anti-tumor effect for breast cancer cells resistant to anti-HER2 drugs." (PMID 35646898, 2022). "Fatty acid synthase (FASN) is required for de novo synthesis of fatty acids and is correlated with poor prognosis in breast cancer patients." (PMID 34948368, 2021). "De novo synthesis of palmitate by fatty acid synthase (FASN) is reported to contribute to mitochondrial epidermal growth factor receptor (mtEGFR) palmitoylation in mtEGFR-positive prostate and breast cancer cell lines." (PMID 34095144, 2021). "Thus, FASN may be an ideal target for chemosensitization in breast cancer chemotherapy." (PMID 34948368, 2021). "In breast cancer, knockdown of β‐catenin led to increased expression of acetyl‐CoA carboxylase (ACC) and FASN, proteins involved in the de novo synthesis of FAs." (PMID 34766135, 2021). "Herein, we sought to clarify the role of FASN in the development and maintenance of hormone-independent growth and resistance to tamoxifen in ER/HER2-positive breast cancer." (PMID 33800852, 2021).
breast cancer (continued). "When ER+ tumors were, in turn, sub-divided according to their HER2 status into ER+/HER2- and ER+/HER2+, the ER+/HER2+ subgroup exhibited the highest FASN protein expression compared to basal-like, HER2-enriched, and ER+/HER2-negative breast cancer groups." (PMID 33800852, 2021). "In breast cancer stem cell sub-populations, high expression levels of ACC 1/2 and FASN have been correlated with increased cell survival and, in turn, with the formation of pre-malignant lesions." (PMID 33808259, 2021). "Herein, taking into account that leptin induces SREBP‐1 in MCF‐7 breast cancer, we have identified SREBP‐1 target genes in response to leptin stimulation, including FASN, ACLY, and FADS2." (PMID 33226729, 2021). "In contrast, a significant relationship between low expression of FASN and poor OS (P = 0.018), poor RFS (P = 3.5e-06), poor DMFS (P = 5.7e-05), and poor PPS (P = 0.022) outcomes was found for breast cancer." (PMID 34879004, 2021). "Reportedly, the methods developed in this study were successful in determining the spatial variation in the expression of 102 genes, including several breast cancer biomarkers such as GNAS, FASN, and DDX5." (PMID 34441338, 2021). "Data suggest that in breast cancer cell lines overexpressing HER2, both FASN and ACC1 levels increased compared with cells in which HER2 expression is relatively low (such as MDA-MB-231)." (PMID 33808259, 2021). "FASN inhibition in MCF-7 and BT-474 cells leads to downregulation of Akt and thus overall breast cancer survival." (PMID 34298660, 2021). "Functional cancer proteomic data from The Cancer Proteome Atlas (TCPA) revealed that the ER+/HER2+ subtype was the highest FASN protein expressor compared to basal-like, HER2-enriched, and ER+/HER2-negative breast cancer groups." (PMID 33800852, 2021). "Apart from the PI3K/AKT pathway, a similar observation can be seen in breast cancer cells, which identifies leukotriene B4 (LTB4) as the downstream product of 5-lipoxygenase (5-LOX), that induces FASN expression." (PMID 32872164, 2020). "Treatment of breast cancer cell lines, SKBR3 and MCF-7, with cerulenin inhibits FASN activity, reduces clonogenic properties and induces programmed cell death." (PMID 32872164, 2020). "In osteosarcoma and breast cancer cells, miR-195, by direct targeting the 3′-UTR of FASN, also reduced cell survival, proliferation, invasion, and metastasis." (PMID 33050166, 2020). "We have previously shown the ability of the natural compound EGCG to inhibit FASN activity in wild type EGFR NSCLC cells and different breast cancer subtypes." (PMID 32438613, 2020). "A genome-wide study on the breast cancer cell line, MDA-MB-435, also reiterates the ability of FASN to regulate various metabolic pathways." (PMID 32872164, 2020). "In breast cancer cell lines, MCF-7 and SKBR3, Small ubiquitin-like modifier (SUMO)-conjugating enzyme Ubiquitin carrier protein 9 (UBC9) is shown to promote FASN sumoylation." (PMID 32872164, 2020). "In SKBR3, a HER2 overexpressing breast cancer cell line, heregulin stimulation promotes phosphorylation and heterodimerization of HER2 leading to FASN phosphorylation." (PMID 32872164, 2020). "In breast cancer cells, inhibition of ACC and FASN results in impaired cancer cell migration and invasion." (PMID 33302403, 2020). "TVB-2640 is currently being investigated in a Phase II clinical study (NCT03179904), combining FASN inhibition with trastuzumab and paclitaxel for the treatment of late stage HER2+ breast cancers." (PMID 32226926, 2020). "C75 and orlistat are used for FASN inhibition; the FASN inhibitor, FASNall, effectively reduces tumor burdens in HER2+ breast cancer." (PMID 33081387, 2020).